ALB (albumin)
Diseases named in the same sentence as ALB in open-access papers (continued):
Sharing a sentence is not in itself a finding about the gene and the disease.
cancer (continued). "Compared with the previous prognostic tools in ESLD, our study demonstrated that albumin was the protective indicator of non-cancer ESLD survival." (PMID 30240398, 2018). "AGR, obtained by dividing the serum albumin level by the globulin level, is a valuable indicator that reflects both systemic nutritional and systemic inflammatory status in cancer patients with a single measurement." (PMID 29757575, 2018). "In fact, more and more evidence indicated that the cancer cachexia is reflected by a reduction in the level of albumin." (PMID 29466970, 2018). "A preclinical study shows that Cav-1 expression mediates albumin uptake in cancer cells and directly determines the uptake of nab-paclitaxel in cancer cells." (PMID 30348118, 2018). "Previous studies have shown copper alone to be cytotoxic against cancer cells, albeit at a concentration above 100 μM, although copper nanoparticles coated with albumin displayed cytotoxicity in TNBC cells above 50 μM." (PMID 30388728, 2018). "Research showed that several inflammation markers are associated with cancer, such as inflammation-based prognostic score based on C-reactive protein(CRP )and albumin levels." (PMID 29515785, 2018). "A recent meta-analysis of 29 studies on variety of gastrointestinal tract solid tumors reported that pretreatment serum albumin levels provide useful prognostic significance in cancer." (PMID 30116261, 2018). "This is particularly important in patients with advanced cancer in whom albumin levels are frequently low." (PMID 30236112, 2018). "Postoperative lower serum albumin level (p < 0.001) and primary cancer site over hypopharynx (p = 0.018) were both significantly associated with higher probability of postoperative major wound infection." (PMID 29576961, 2018). "Several drug delivery systems that carry anti-cancer chemotherapeutic agents have been tested in patients with cancer, including liposomes, lipid core nanoparticles, albumin nanoparticles, and polymeric nanoparticles." (PMID 29581835, 2018). "Serum albumin has also been investigated as a predictor of cancer survival and perioperative outcomes in a variety of cancers." (PMID 29576961, 2018). "This dendrimer–nanoparticle assembly provides a novel way of targeting drugs to the cancer cells compared to paclitaxel and albumin nanoparticles." (PMID 29670005, 2018). "Our experiments confirm that HepaRG exhibit profoundly elevated levels of expression of cytochromes P450 3A4 and 2C9, albumin and α-antitrypsin compared to cancer cell lines." (PMID 30567412, 2018). "In the present study, we found that the lower the serum albumin level, the poorer the prognosis in non-cancer ESLD patients." (PMID 30240398, 2018). "The mGPS combines albumin and CRP into a prognostic risk stratification score for predicting the clinical outcome in cancer patients." (PMID 29467943, 2018). "Given that the CRP/albumin ratio also shows various cut-off values depending on cancer type and severity, further studies will be needed to better understand the optimal cut-off value for the hsCRP/albumin ratio in different clinical scenarios." (PMID 29880755, 2018). "In recent years, many studies have indicated that preoperative serum albumin level can serve as an indicator of inflammation and is closely related to the prognosis of various types of cancers." (PMID 29685957, 2018). "Herein, we introduce a facile and oil-free method to prepare albumin-based PTX nanoparticles for efficient systemic cancer therapy using a conjugate of human serum albumin (HSA) and poly(ethyleneglycol) (PEG)." (PMID 30044159, 2018). "Previous studies have shown that the C‐reactive protein/albumin ratio (CAR) is a prognostic indicator in multiple types of carcinomas." (PMID 29193777, 2018). "Serum albumin levels fall sharply in patients with advanced cancer due to malnutrition and systemic inflammatory responses to malignancy." (PMID 28476041, 2017).
cancer (continued). "The preoperative C-reactive protein/Albumin ratio (CAR) is valuable for predicting the prognosis of patients with various types of cancers." (PMID 29228679, 2017). "The cytotoxicity of copper nanoparticles on cancer cell is accelerated by placing CuNPs in albumin nanoparticles carrier, possibly due to the increased uptake of the CuNPs." (PMID 29186208, 2017). "This concept was commonly known to be exploited in the albumin-paclitaxel formulation (Abraxane) for anti-cancer therapy." (PMID 29185444, 2017). "Serum albumin levels are an important indicator of host's systemic inflammatory response and nutritional status as a prognostic indicator in several cancer." (PMID 28548947, 2017). "The resulting albumin/AlbiVax nanocomplexes that assemble in vivo were efficiently delivered to LNs and induced potent and durable anti-cancer immunity." (PMID 29203865, 2017). "IL-1β levels strongly associated with subjective (weight loss, loss of appetite) and objective (albumin and CRP levels) measurements of cancer cachexia." (PMID 28177923, 2017). "The Glasgow Prognostic Score (GPS) combines albumin and CRP into a risk stratification score for the prognosis of clinical outcome in cancer patients." (PMID 28717855, 2017). "We chose albumin, one of the most successful carriers of nanomedicines in the clinic, to deliver anti-cancer molecular vaccines in this study." (PMID 29203865, 2017). "The albumin served as a source for glutamine, a major nutrient that can support the cancer cells' metabolic needs." (PMID 28071763, 2017). "Inflammatory cytokines such as TNF-α contribute to decreased albumin production, and albumin levels can be used as a prognostic indicator for cancer." (PMID 27974681, 2017). "Seven independent risk factors for OS were selected from cohort 1, including the male sex, age ≥ 70 years, the presence of a malignancy, body mass index <18.5 kg/m2, lymphocyte count <1000 cells/μL, serum albumin levels <3.5 g/dL, and fibrocavitary disease." (PMID 28629426, 2017). "Herein, we evaluate the effect of macrophage phenotype on the transport and anti-cancer efficacy of albumin-bound paclitaxel (nAb-PTX) loaded into porous silicon multistage nanovectors (MSV)." (PMID 28670313, 2017). "For example, as a SIR marker, incorporating C-reactive protein (CRP), together with serum albumin, has a close relationship with outcomes in cancer patients." (PMID 29179480, 2017). "Taken together, higher serum albumin levels were considered a protective factor for cancer patients." (PMID 28076328, 2017). "Beside that nutritional role, serum albumin level represents a marker for inflammatory response in cancer patients as well." (PMID 28740506, 2017). "Recent studies have shown inflammation-based prognostic scores, including Glasgow prognostic score (GPS), modified Glasgow prognostic score (mGPS), and CRP/Albumin (C/A) ratio to be a significant prognostic indicator in many cancers, including EC." (PMID 28740506, 2017). "In the progress of many diseases, including cancer, infection, inflammation, a low-level of serum albumin has been identified." (PMID 28446147, 2017). "As components of the PNI, both the albumin count and the lymphocyte count are closely related to inflammatory responses in cancer patients, which are independent predictors of long-term outcomes in OC25,26." (PMID 28842710, 2017). "For cancer patients an inverse relation between BMI and albumin is described, which has been attributed to an enhanced compensatory synthesis." (PMID 29113384, 2017). "The C-reactive protein/albumin ratio (CAR) has been shown to play a significant prognostic role in several cancers." (PMID 28128229, 2017). "Herein, we developed a novel nanocomposite of CuNPs covered by albumin as a nanocarrier and assayed its cytotoxic properties against invasive human cancer cell line of MDA-MB-231 for the first time." (PMID 29186208, 2017).
cancer (continued). "Albumin is a central element of plasma proteins conserving the colloidal osmotic pressure and imitates the nutritional status of cancer patients." (PMID 28740506, 2017). "Because of the higher rate of metabolism in cancer cells, the albumin uptake also proceeds by these cells." (PMID 28701707, 2017). "As to now, there are no data regarding the predictive value of liver parameters, especially BChE or albumin, in an unselected cohort of cancer patients." (PMID 29113384, 2017). "This phenomenon is probably due to enhancement of the albumin internalization in cancer cells and subsequent increase of the intracellular levels of CuNPs." (PMID 29186208, 2017). "Previous studies showed that albumin alone or albumin-based markers were independent predictors of poor survival in several cancers." (PMID 28076328, 2017). "The GPS, which takes into account the serum CRP and albumin levels, simply reflects the systemic inflammation status of patients with cancer and their prognosis, as described for various cancer types." (PMID 28717855, 2017). "Albumin, on the contrary, provides abundant anti-oxidative substances and is proposed as a protective factor for cancer patients." (PMID 28076328, 2017). "The literature review by Gupta also reports that the most effective factor in the prognosis of patients with cancer is serum albumin level." (PMID 26782276, 2016). "GPS and mGPS are inflammation-based prognostic scores developed by combining CRP and albumin to predict the clinical outcomes in cancer patients." (PMID 26880857, 2016). "Multivariate Cox regression showed cancer type to be an independent prognostic factor for OS and serum albumin to be an independent prognostic factor for SP-Survival." (PMID 27103467, 2016). "Albumin NPs have been reported to serve as a promising drug carrier for treating inflammatory diseases and cancer." (PMID 27391073, 2016). "In univariate analysis, CRP, albumin, CEA, and CA19-9 were significantly associated with postoperative cancer-specific survival." (PMID 27632196, 2016). "In conclusion, blood albumin concentration can be used as a marker of a successful completion of cancer chemotherapy before starting chemotherapeutic treatment." (PMID 27863481, 2016). "There is now accumulating evidence that the markers of the systemic inflammatory response, including cytokines, C-reactive protein (CRP), albumin, serum amyloid A and white cell count, can be independent prognostic factors in cancer patients." (PMID 27136467, 2016). "The aim of the work was to determine the interactions of a set of anti-cancer compounds with bovine serum albumin (BSA) using a ProteOn XPR36 array biosensor and molecular docking studies." (PMID 27973422, 2016). "Inflammatory biomarkers, such as neutrophil to lymphocyte ratio (N/L), neutrophil to platelet ratio (N/P), and serum albumin level, hold great promise for improving the predictive ability of existing prognostic tools in cancer patients." (PMID 27036213, 2016). "FA translocation from stromal cells to cancer cells can be mediated by lipoproteins, serum albumin and exosomes." (PMID 26807644, 2016). "To limit the influences, we excluded the patients with incurable cancer because the advancing anticancer therapy in recent years and patients with severe cirrhotic liver from its profound and rigid impact on serum albumin." (PMID 27015223, 2016). "Macropinocytosis appears to be the key player in this phenomenon, as amiloride-based drugs that selectively inhibit macropinocytosis while leaving other coat-dependent endocytosis intact halted intake of albumin as a source of glutamine for cancer cells." (PMID 27672367, 2016). "Serum albumin is an important indicator of the host inflammatory response and nutritional status and has been shown to be related to the prognosis of cancer patients." (PMID 27399281, 2016).
cancer (continued). "Meanwhile, the role of the pretreatment serum albumin levels as an independent predictor of the OS has been demonstrated in various cancers, including PC." (PMID 27344157, 2016). "Firstly, PNI is decided by the serum albumin concentration and lymphocyte count in the peripheral, both of which are obviously correlated with the prognosis of cancer patients." (PMID 27888808, 2016). "Serum albumin is one of the most commonly used indicators of a patient's nutritional status, and it has also been used to assess cancer progression and prognosis." (PMID 27765916, 2016). "The Glasgow Prognostic score relies on inflammatory biological markers (C-reactive protein and serum Albumin) and predicts survival in advanced cancer." (PMID 26859298, 2016). "In a similar fashion to absorbing extracellular albumin, cancer cells have also been shown to internalize extracellular ATP to aid in cancer metabolism." (PMID 27672367, 2016). "Cancer patients included were ≥18 years, and had serum calcium (Ca) and albumin (for corrected serum Ca [CSC]) records." (PMID 27263488, 2016). "Cancer patients exhibit decreased albumin production, in all likelihood mediated by TNFα, as TNFα treatment per se is sufficient to inhibit albumin production in vivo (mice and rabbits), or in isolated hepatocytes in vitro." (PMID 26900952, 2016). "Abraxane® is an established albumin-based nanoparticle system produced by Celgene and is used in the treatment of cancer." (PMID 26925240, 2016). "Recently, the Glasgow prognostic score (GPS), which is based on C-reactive protein (CRP) and albumin levels as well as reflects inflammation and nutritional status, was used as a prognostic indictor for numerous cancers." (PMID 26754834, 2016). "GPS was derived from the acute-phase proteins C-reactive protein and albumin, which were more sensitive and reliable markers that reflect the systemic inflammatory response in cancer patients." (PMID 27854304, 2016). "99mTc-Albures and 99mTc-Nanocoll are both albumin aggregated particles containing the metastable nuclear isotope of technetium-99 that have been used for various diagnostics purposes in cancer and infectious diseases." (PMID 26925240, 2016). "A meta-analysis study has suggested that serum albumin is a reliable index to predict cancer survival." (PMID 27863481, 2016). "A number of studies have also suggested that serum albumin concentration is a mortality prognosis factor in cancer patients." (PMID 27863481, 2016). "The two groups had comparable age, gender, BMI, systolic and diastolic blood pressure, serum albumin and creatinine, cancer stage, and smoking and drinking habits." (PMID 27051670, 2016). "Celgene has a portfolio of albumin-based nanoparticles for cancer treatment, which have been presented in a report by Desai." (PMID 26925240, 2016). "Other albumin-based conjugates targeting folate receptors also demonstrated efficient delivery of cytotoxic compounds specifically into cancer cells." (PMID 27672367, 2016). "These suggest that albumin nanoparticles have the potential to function as a carrier for anti-cancer therapeutics, including liver tumors." (PMID 26404356, 2015). "Nanodrugs in liposome‐ or albumin‐based formulations are already used in the clinic for some forms of cancers, and others are being tested in pre‐clinical trials." (PMID 26589247, 2015). "It was also reported that as the inflammation due to cancer increased, the serum albumin concentration of the patients decreased." (PMID 26147805, 2015). "Nutritional status of cancer patients, commonly reflected by serum albumin, is also a determinant of survival in many kinds of cancer." (PMID 26656866, 2015). "In previous studies, both the serum albumin and serum globulin concentrations have been reported to be prognostic factors for survival in patients with various types of cancers." (PMID 25934494, 2015).
cancer (continued). "The bioabsorbable materials that are commonly used in cancer therapy are polyesters, polyanhydrides, polyphosphoesters, polysaccharides (e.g., chitosan, dextran, hyaluronic acid), and proteins (e.g., albumin, gelatin)." (PMID 26605001, 2015). "We next determined the effect of LP- and HP-albumin treatment on lipid levels in cells cultured under SSH as LCFA uptake results in cytoplasmic lipid droplet accumulation in cancer cells." (PMID 25879517, 2015). "Serum albumin has been used to evaluate prognosis of numerous cancers, including UTUC, and the results of those studies have been fairly consistent: lower serum albumin is an independent predictor of poorer clinical outcome." (PMID 26681341, 2015). "In the development of DDS for cancer therapy, the use of albumin can bring some advantages since this protein is used by the proliferating tumor cells for their nutrition, being readily taken up by a fluid phase endocytosis, followed by lysosomal breakdown." (PMID 26605001, 2015). "To date, several measurements of systemic inflammatory response, such as NLR, platelet-to-lymphocyte ratio, C-reactive protein, and serum albumin, have been investigated in cancer patients." (PMID 26469891, 2015). "A prognostic nutritional index, calculated using serum albumin levels and peripheral lymphocyte count, has been used to assess prognosis for various cancers." (PMID 26356222, 2015). "The basis of the independent prognostic value of C-reactive protein, albumin and neutrophil count over all disease states (and platelets in cancer) is likely to be complex." (PMID 25730322, 2015). "The pretreatment albumin to globulin ratio (AGR) has been reported to correlate with the long-term survival in patients with various cancers." (PMID 25934494, 2015). "In cancer patients (including HCC) low serum albumin predicts a poor response to treatment and poor survival and a large proportion of HCC patients have ROS damaged serum albumin." (PMID 25806803, 2015). "Together with leukocytes, albumin has been studied as a marker of systemic inflammation in the context of cancer survival and so far results have shown that low levels of albumin and high levels of leukocytes are associated with worse cancer prognosis." (PMID 26284119, 2015). "GPS, which is a combination of CRP and albumin levels, reflects the effects of systemic inflammatory response and the process of nutritional decline in advanced cancer." (PMID 24885814, 2014). "ALB is most commonly used to assess nutritional status, and is also a useful factor for predicting the prognosis of patients with cancer." (PMID 24718309, 2014). "A cutoff age of 60 years was more suitable, was retained in the model, and was a stronger predictor (having the highest odds ratio) for cancer than the other 2 variables (albumin and ALP)." (PMID 24762986, 2014). "Proteolysis is the main process during cancer-cachexia, and this can be assessed by a decrease in albumin content, followed by the catabolism of skeletal muscle cells, promoting atrophy and apoptosis." (PMID 24383706, 2014). "In multivariable analysis with these variables dichotomized with all patients, only low albumin (OR = 2.6, CI [1.3–5.2]), and high ALP (OR = 2.3, CI [1.7–4.7]) were associated with cancer." (PMID 24762986, 2014). "In multivariable analysis (quantitative variables), only albumin, ESR, iron, white blood cell count, and LDH levels were associated with cancer." (PMID 24762986, 2014). "Bivariate analysis showed that serum albumin, CRP, ESR, ALP, iron, LDH, white blood cell count, hemoglobin, and ferritin levels were associated with cancer." (PMID 24762986, 2014). "The fact that 98% of the plasma tasquinimod is albumin bound has mechanistic consequences for its high potency as an anti-cancer drug." (PMID 25193858, 2014). "CRP, serum ALB, and peripheral lymphocyte count in cancer patients have recently attracted research attention." (PMID 25022764, 2014).